USP8 (ubiquitin specific peptidase 8)
Diseases named in the same sentence as USP8 in open-access papers (continued):
Sharing a sentence is not in itself a finding about the gene and the disease.
pancreatic cancer (continued). "Hence, targeting USP8 sensitized anti-PD-L1 immunotherapy via regulation of PD-L1 degradation in pancreatic cancer." (PMID 38638430, 2024). "In pancreatic cancer, ubiquitin-specific protease 8 (USP8) catalyzes the deubiquitination of PD-L1 by inhibiting ubiquitin-regulated proteasome degradation, the combined therapy of USP8 inhibitors with anti-PD-L1 effectively inhibits pancreatic tumor growth by activating cytotoxic T cells." (PMID 38762484, 2024). "In a recent study, the ubiquitin-specific protease 8 (USP8) has been shown to de-ubiquitinate PD-L1 in pancreatic cancer, demonstrating that USP8 intervention might increase PD-L1 blockade." (PMID 37296972, 2023). "Targeting USP8 may enhance the effectiveness of immunotherapy for pancreatic cancer." (PMID 39223632, 2024). "Elevated USP8 expression has been identified in various digestive system tumors, including gastric cancer, hepatocellular carcinoma (HCC), cholangiocarcinoma, and pancreatic cancer." (PMID 41301681, 2025). "Among the previously known and here confirmed interactors (CDH1, DISP1, SCFD1, USE1, TSG101, and USP8), CDH1 (E‐cadherin), a critical adhesion molecule, is frequently lost or downregulated in pancreatic cancer, promoting epithelial‐to‐mesenchymal transition (EMT) and enhancing tumor invasiveness." (PMID 40952239, 2025).
pituitary tumor (14 papers, 2018 to 2025). A benign or malignant neoplasm affecting the pituitary gland. "The clinical relevance that hotspot mutations in the USP8 gene cause Cushing’s disease derived from a pituitary tumor supports the critical roles of USP8 in cellular functions." (PMID 38180476, 2024). "The pleiotropic effect of USP8 mutations is clearly reflected by altered gene expression profile in USP8-mutated corticotroph pituitary tumors as compared to USP8 wild-type (USP8wt) corticotroph PitNETs." (PMID 36428684, 2022). "On the contrary, a strong reduction of ACTH release was achieved in primary cultured cells from one ACTH-secreting pituitary tumor bearing the P720R USP8 mutation incubated with pasireotide (#7) (−46.4 ± 11% secretion vs. basal p < 0.05)." (PMID 35626057, 2022). "Somatic mutations in USP8 gene have been identified in 11–60% of patients with ACTH-secreting pituitary tumors." (PMID 35626057, 2022). "Accordingly, no pasireotide antisecretory effect was observed in primary cultured cells from one ACTH-secreting pituitary tumor endogenously carrying the S718P USP8 mutation (#6)." (PMID 35626057, 2022). "Overall these data demonstrate that different USP8 mutations exert opposite effects on the responsiveness of ACTH-secreting pituitary tumors to pasireotide." (PMID 35626057, 2022). "Almost half of ACTH-secreting pituitary tumors were reported to develop because of ubiquitin-specific peptidase 8 (USP8) somatic mutation, which leads to an increased USP8 deubiquitinating activity and triggers the release of adrenocorticotropic hormone (ACTH)." (PMID 35528020, 2022). "USP8-mutated pituitary tumors mostly displayed high immunoreactivity of USP8 in the nuclei." (PMID 34439178, 2021). "Moreover, mutations in the Usp8 and Usp48 loci in pituitary tumors cause Cushing syndrome." (PMID 36834633, 2023). "The recent identification of somatic mutations in the 14-3-3 protein binding motif of ubiquitin specific peptidase 8 gene (USP8), present in a consistent subgroup of ACTH-secreting pituitary tumors, have represented a major advance in the understanding of CD pathogenesis." (PMID 34439178, 2021). "Epigenetic modifications have become increasingly important in understanding tumorigenesis, as most pituitary tumors are sporadic with no known genetic driver mutations (with the exception of a significant proportion of GH-PTs and ACTH-PTs with GNAS and USP8 mutations, respectively)." (PMID 32201880, 2020).
hepatocellular carcinoma (12 papers, 2021 to 2026). A malignant tumor that arises from hepatocytes. "We investigated the role of USP8 in hepatocellular carcinoma (HCC) by analyzing expression patterns of USP8 in HCC patients, and evaluating its functions and underlying signaling." (PMID 34081623, 2021). "For instance, in hepatocellular carcinoma, USP8 inhibition induces ferroptosis by destabilizing OGT, thereby disrupting SLC7A11-mediated cystine uptake." (PMID 40813720, 2025). "The deubiquitinase ubiquitin-specific peptidase 8 (USP8) is found to inhibit cancer cell proliferation and induce cell ferroptosis in hepatocellular carcinoma." (PMID 41005476, 2025). "USP8 inhibitor aids in overcoming hepatocellular carcinoma resistance via suppressing receptor tyrosine kinases." (PMID 40246814, 2025). "The researchers incorporated lipopolysaccharide (LPS), a key component of Gram-negative bacteria and potent TLR4 activator known to modulate the tumor immune microenvironment, in their investigation of USP8-mediated hepatocellular carcinoma regulation." (PMID 40607251, 2025). "In hepatocellular carcinoma models, USP8 inhibition suppresses tumor growth and metastasis by inducing ferroptosis through OGT destabilization to disrupt OGT-SLC7A11 axis; USP8 promotes cancer progression by stabilizing β-catenin and inhibiting ferroptosis." (PMID 40813720, 2025). "Inhibition of USP8, by stabilizing OGT and impacting cystine uptake via SLC7A11, effectively suppresses hepatocellular carcinoma progression and induces ferroptosis, suggesting its potential as a therapeutic target for HCC treatment." (PMID 39315094, 2024).
cholangiocarcinoma (7 papers, 2021 to 2025). A carcinoma that arises from the intrahepatic biliary tree (intrahepatic cholangiocarcinoma) or from the junction, or adjacent to the junction, of the right and left hepatic ducts (hilar cholangiocarcinoma). "Recently, Another study indicated that proliferation, viability, and colony formation of cholangiocarcinoma cells were all considerably decreased after USP8 silencing but it didn’t explain the deep mechanism of this phenomenon." (PMID 38973004, 2024). "Regarding USP8, its tumor-promoting functions have been reported in several cancer types, and its inhibition reduces the invasion of cholangiocarcinoma cells." (PMID 36816802, 2023). "extended the apoptotic activity of USP8 in cholangiocarcinoma cells, where the silencing of USP8 was reported to decrease Bcl-2 expression and increase Bax, cleaved Caspase 3, and cleaved Caspase 9 expression and thereby triggering apoptosis." (PMID 36338727, 2022). "The depletion of USP8 promotes intrinsic apoptosis by suppressing AKT activity in cholangiocarcinoma (CCA)." (PMID 33919439, 2021). "This review synthesizes current knowledge on six USP members—USP1, USP3, USP8, USP9X, USP21, and USP22—and delineates their context-dependent roles across cholangiocarcinoma and GBC subtypes." (PMID 41301681, 2025).
gastric cancer (7 papers, 2022 to 2025). A primary or metastatic malignant neoplasm involving the stomach. "For instance, USP7 has been shown to suppress ferroptosis by activating stearoyl-CoA desaturase in gastric cancer, whereas USP8 knockdown enhanced ferroptosis through inhibiting GPX4 in CRC." (PMID 40962058, 2025). "Novel USP8 inhibitors were further discovered and exhibited anticancer efficiency, and treatment with the USP8 inhibitor or siRNA targeting USP8 was reported to inhibit HER-3-positive gastric cancer cell growth." (PMID 36816802, 2023). "In multiple studies, the EGFR is a substrate of USP8 deubiquitination, while USP8 has been shown to enhance gastric cancer cell proliferation and metastasis via the PI3K/AKT signaling pathway." (PMID 36338727, 2022). "USP8 inhibited the migration and proliferation of HER-2 positive gastric cancer cells through the PI3K/AKT signaling pathway." (PMID 36539510, 2023).
melanoma (7 papers, 2020 to 2025). A malignant, usually aggressive tumor composed of atypical, neoplastic melanocytes. "In fact, USP8 is highly expressed and plays an oncogenic role in melanoma, and inhibition of USP8 suppresses the proliferation of glioblastoma stem cells." (PMID 32825105, 2020). "The more interesting ones, confirmed by the bibliography on melanoma, are as follows: USP15, TIPIN, TMC5, TYMP, USP19, USP8, and TFAP2B." (PMID 38928466, 2024). "The high expression of NOTCH2 and USP8 has been correlated to a worse prognosis in many tumor types, including SCC, and melanoma." (PMID 39456581, 2024). "For melanoma, all module two genes are present in COSMIC, and two of these genes, USP8 and PPFIBP1 are known oncogenes present in OncoKB." (PMID 34570764, 2021).
cervical carcinoma (6 papers, 2019 to 2024). A carcinoma arising from either the exocervical squamous epithelium or the endocervical glandular epithelium. "High expression of USP8 is associated with poor prognosis in patients with cervical cancer and early-stage lung adenocarcinoma." (PMID 34081623, 2021). "Consistently, high expression of USP8 was correlated with advanced tumor stage and high recurrence risk in cervical cancer patients." (PMID 34081623, 2021). "USP8 plays a vital role in potentiating cell proliferation in lung and cervical cancers, leading to cell cycle dysregulation and accelerated apoptosis." (PMID 36644233, 2023). "Inhibition of USP8 has been shown to decrease NRDP1 levels and decrease cell proliferation and drug resistance in several cancers including breast, lung, and cervical cancer." (PMID 34503235, 2021).
cervical squamous cell carcinoma (6 papers, 2019 to 2024). A squamous cell carcinoma arising from the cervical epithelium. "USP8 protein was rarely expressed in normal cervical tissues, but its expression was increased in cervical squamous cell carcinoma (CSCC) tissues, especially in advanced CSCC." (PMID 38973004, 2024). "When exploring the clinical role of USP8, we found that it was an independent prognostic factor for adverse outcome, in keeping with reports on cervical squamous cell carcinoma in which high expression is related to poor survival." (PMID 36578788, 2022). "Aberrant upregulation of USP8 was also observed in other cancers, such as cervical squamous cell carcinoma and lung adenocarcinoma." (PMID 34081623, 2021).
glioblastoma (6 papers, 2016 to 2023). The most malignant astrocytic tumor (WHO grade IV). "In fact, Akt activation has been shown to decrease USP8 function in glioblastoma cells, whereas in breast tumor cells Akt activation appears to lead to increased USP8 activity." (PMID 36578788, 2022). "Additionally, USP8 linked the PTEN-Akt-AIP4 pathway to the regulation of FLIPS stability and TRAIL sensitivity in Glioblastoma Multiforme." (PMID 36539510, 2023). "In a recent example, the Dirks and Angers groups used genome-wide CRISPR screening and identified USP8 as one of the vulnerable genes from patient-derived glioblastoma stem cells and then validated USP8 to be an actionable therapeutic target using the lentiviral delivery of a UbV inhibitor." (PMID 35625630, 2022). "Inhibitor treatment revealed that USP8 is required for growth of glioblastoma stem cells, multiple myeloma cells and gefitinib-resistant non-small cell lung cancer cells and demonstrated the existence of a therapeutic window in comparison with growth inhibition of control cells." (PMID 31845722, 2019). "USP8 and USP9X deubiquitinate ITCH to induce ubiquitination and degradation of the anti-apoptotic protein c-FLIP, leading to apoptosis in glioblastoma, or to anoikis in pancreatic ductal adenocarcinoma." (PMID 27203743, 2016). "One study showed that USP8 acts downstream of PTEN to enhance the ability of the E3 ligase Itch to reduce cFLIPS stability and increase tumor necrosis factor-related apoptosis-inducing ligand (TRAIL) sensitivity in human glioblastoma multiforme cells." (PMID 31845722, 2019).
liver cancer (6 papers, 2022 to 2025). An epithelial or non-epithelial malignant neoplasm that arises from the liver. "For example, USP8 promotes proliferation, invasion and tumour cell stemness in liver cancer by stabilising β‐catenin mediated ferroptosis." (PMID 39661501, 2024). "USP22, USP14, USP10, USP13, USP7, USP2, and USP8, liver cancer-related DUBs, have also been reported to have related small molecule inhibitors, but the research and development are not mature enough." (PMID 35875077, 2022). "USP8 can regulate the expression of multiple receptor tyrosine kinases (RTKs) to affect the drug resistance of liver cancer cells." (PMID 35875077, 2022). "Compared with normal liver tissue, USP8 is significantly upregulated in liver cancer tissue." (PMID 40607251, 2025). "Consistently, in the presence of cycloheximide (CHX, an inhibitor of protein translation), inhibition of USP8 promoted the degradation of endogenous FTL protein in human liver cancer cell line HepG2 and overexpression of USP8 delayed the protein turnover of exogenous FTL protein in HEK 293T cells." (PMID 37051673, 2023). "Meanwhile, USP8 regulated liver cancer cell progression via inhibition of TRAF6-mediated signaling." (PMID 36539510, 2023).
non-small cell lung carcinoma (6 papers, 2019 to 2025). A group of at least three distinct histological types of lung cancer, including non-small cell squamous cell carcinoma, adenocarcinoma, and large cell carcinoma. "Biologically, non-small cell lung cancer (NSCLC) tumor xenografts with reduced USP8 protein expression, when treated with SAIT301, significantly demonstrated a reduction in tumoral growth and of c-Met expression compared to the non-treated group." (PMID 34577547, 2021). "The USP8 inhibitor 9-ethyloxyimino-9H-indeno[1,2-b] pyrazine-2,3-dicarbonitrile suppresses growth of non-small cell lung carcinoma (NSCLC) cells." (PMID 34272356, 2021).
colorectal cancer (5 papers, 2019 to 2025). A primary or metastatic malignant neoplasm that affects the colon or rectum. "Studies have shown that the knockdown or pharmacological inhibition of USP8 increases the sensitivity of colorectal cancer cells to ferroptosis and that USP8 interacts with GPX4 and prevents GPX4 protein degradation by affecting GPX4 deubiquitination." (PMID 40136465, 2025). "Promising therapeutic targets include USP8, the USP8-Trichoplein-AurA pathway, and USP54, which may enhance ciliogenesis and inhibit tumor progression, particularly in colorectal cancer." (PMID 40277920, 2025).
Parkinson disease (5 papers, 2018 to 2026). A progressive degenerative disorder of the central nervous system characterized by loss of dopamine producing neurons in the substantia nigra and the presence of Lewy bodies in the substantia nigra and locus coeruleus. "The USP family member USP8 is found in Lewy bodies, a neuropathological hallmark of Parkinson’s disease composed of lipids and α-synuclein inclusions." (PMID 33483467, 2021). "In addition, this study identifies USP8 as one of the best markers of Lewy bodies in human pigmented neurons in sporadic cases of Parkinson’s disease and demonstrates the ability of USP8 to hydrolyze K63-linked ubiquitin chains from α-synuclein in vitro." (PMID 30126257, 2018). "Studies have shown that in Parkinson's disease, inhibiting the expression of USP8 would lead to a delay in the occurrence of mitophagy and a reduced success rate, thereby affecting the quality control process of mitochondria." (PMID 38376054, 2024). "USP8 appears to have opposing roles in the context of Parkinson’s disease by either stabilizing α-synuclein levels or promoting parkin-mediated mitophagy." (PMID 33483467, 2021). "As one of the deubiquitinases, which play a critical role in regulating synaptic function and whose dysfunction results in several neurological disorders, USP8 has been shown to be associated with AD42, Parkinson’s disease, and Lewy body disease." (PMID 34654853, 2021). "Moreover, Usp8 gene extinction significantly reduces the total level of α-synuclein both in a Drosophila model of Parkinson’s disease and in human embryonic kidney (HEK293T) cultured cells." (PMID 30126257, 2018). "Besides, USP8 could regulate mitophagy process via modulating Parkin activity, while pharmacological targeting USP8 could rescue the phenotype of Parkinson’s disease." (PMID 41565619, 2026).
bladder cancer (4 papers, 2022 to 2024). "One compound ChlA-F blocked cell invasion via inhibition of SOX2 protein by USP8-mediated SOX2 degradation in bladder cancer." (PMID 37215134, 2023). "Meanwhile, HuR increases mRNA stability and protein level of ubiquitin-specific protease 8 (USP8) as a result of its posttranscriptional regulation, which was determined to be the case in bladder cancer." (PMID 35658874, 2022). "In vivo studies confirmed the downregulation of PTEN and USP8, as well as their positive correlations in both BBN-treated mouse bladder urothelium and tumor tissues of bladder cancer in nude mice." (PMID 38365726, 2024). "Another study revealed that USP8 can regulate SOX2 ubiquitination and degradation in bladder cancer." (PMID 37215134, 2023). "USP8 plays a significant role in the p52/miR-145/Sp1/USP8/AUF1/RhoGD1β axis, which can act as a positive regulator of bladder cancer invasion." (PMID 37497216, 2023).
hypercortisolism (4 papers, 2022 to 2025). "In conclusion, we report progression of isolated growth hormone deficiency due to a germline GH1 variant to combined pituitary hormone deficiency followed by hypercortisolism due to an ACTH-secreting macroadenoma with a somatic variant in USP8 in the same patient." (PMID 35029852, 2022). "The association of more severe hypercortisolism with USP8 variants was also not found; all patients who died, and those who underwent BLAE, harbored a USP8-WT tumor." (PMID 39684597, 2024).